MMP2 (matrix metallopeptidase 2)
Diseases named in the same sentence as MMP2 in open-access papers (continued):
Sharing a sentence is not in itself a finding about the gene and the disease.
tumor (continued). "However, MMP-2 indicated a limited value for tumor staging and prognosis in OC, suggesting better usefulness of TIMP-2 as a potential tumor marker, particularly when combined with SCC-Ag." (PMID 38673838, 2024). "Additionally, endostatin exerts anti-proliferative effects by inhibiting MMP-2 activation and activity, hindering the invasiveness of ECs and tumor cells." (PMID 38672182, 2024). "Furthermore, the overexpressed MMP2 in tumor tissues degraded the responsive peptides in the nanoparticles, triggering their disintegration in the extracellular environment and subsequent release of the encapsulated protein drugs." (PMID 39439489, 2024). "The evaluation of the effectiveness of the studied compounds was based on their cytotoxicity, effect on the cell cycle, as well as the expression of key genes of the Hh signaling pathway (Ptch1, Smo, Gli1) and putative target genes of molecules involved in tumor progression: MMP-2 and MMP-9." (PMID 39274874, 2024). "In both brain and tumor samples, relative mRNA expression of key proline cycle enzymes, that is, POX/PRODH, PYCR1, PYCR2, and PYCR3, were evaluated, along with the expression of genes associated with ECM degradation, i.e., PEPD, MMP-2, and MMP-9." (PMID 38275897, 2024). "CTX could specifically interact with matrix metalloproteinase-2 (MMP-2) and impede MMP-2 activity, which may affect tumor metastasis process." (PMID 38318188, 2024). "Additionally, MMP2 upregulation can facilitate tumor cell invasion by breaking down the ECM, while Claudin-1 downregulation can disrupt cell–cell adhesion during the process of EMT." (PMID 38400838, 2024). "Interestingly, in our study, we found that hydrogen treatment actually alleviated ROS in CAFs and down‐regulated a key ROS‐induced gene, Nos2, and down‐stream pro‐tumor factors such as Mmp2, Cxcl1, and Cxcl12." (PMID 38757665, 2024). "Furthermore, POLQ knockdown distinctly reduced the expression levels of MMP2 and MMP9, which were associated with tumor metastasis and invasion." (PMID 39520627, 2024). "MMP-2 and MMP-9, among all MMP members, have been linked to tumor metastasis." (PMID 36785788, 2023). "Our data indicate that MMP2 in lung fibroblasts is regulated by linc00881 of exosomes derived from OS, which promotes the release of cytokines, thus activating the NF-KB signaling pathway and establishing the microenvironment before tumor metastasis." (PMID 37990331, 2023). "This nanoparticle could externalize its inner PS triggered by overexpressed matrix metalloproteinase 2 (MMP2) in the tumour site." (PMID 37461033, 2023). "In addition, a variety of cytokines, including TNF-alpha (TNF-α), TGF-beta (TGF-β), MMP2 (matrix metalloproteinase-2), and MMP3, are associated with the proliferation, invasion and metastasis of tumor cells." (PMID 37895145, 2023). "The liposomes were disassembled into two functional parts upon MMP-2 cleavage at the tumor site." (PMID 36762192, 2023). "MMP-2 has been reported to correlate with tumor metastasis in many cancer types." (PMID 36639546, 2023). "Interestingly, in endometrial cancer cells both Rac1—an indicator of tumor cell migration and invasion, and MMP-2—an indicator of tumor metastasis and primary tumor growth—were downregulated by IL-37." (PMID 36769226, 2023). "To understand the molecular mechanism through which integrin β3 regulated cell invasion, we performed Western blot to detect the protein levels of the tumor cell invasiveness inducers, MMP2 and MMP9 (Supplementary Fig5A, 5C), in ITGB3 interfered cells and control cells." (PMID 36944577, 2023). "Moreover, another gene, MMP-2, which is produced by tumor cells, plays important roles in tumor invasion, including HCC." (PMID 38025527, 2023). "Furthermore, immunostaining of the tumor tissues showed lower expression of Ki-67 and MMP-2 in the shZYX group compared to that in the control group, as opposed to increased expression in the PCDH-ZYX group." (PMID 37547758, 2023).
tumor (continued). "Incubation with tumor-derived EVs induced a significant upregulation of MMP2 gene expression." (PMID 37569393, 2023). "When MMP-2 was overexpressed in the TME, GEM-conjugated small nanoparticles (DGL/GEM) are released from DGL/GEM@PP/GA, causing the large nanoparticles (PP/GA) loaded with 18beta-glycyrrhetinic acid (GA) to accumulate at the tumor site." (PMID 37496657, 2023). "MMP-2 inhibition induces apoptotic cell death and suppresses tumor growth." (PMID 36980765, 2023). "The increase of MMP-2 activity and expression is closely related to the invasion and metastasis potential and prognosis of a variety of human malignant tumors 52, so it has become the hotspot of tumor invasion and metastasis research in recent years." (PMID 37283793, 2023). "Considering the metastasis stage, TLR2 triggers the NF-κB activation to signal the induction of the proinflammatory responses and overexpression of type 1 matrix-bound metalloproteinase (MT1-MMP) in microglia thereby activating tumor-released MMP2 that promotes metastasis." (PMID 37822929, 2023). "Selenite inhibits tumor cell invasion by inhibiting the expression of MMP-2, MMP-9, and uPA." (PMID 37006921, 2023). "Thus, EGCG exerts inhibitory effects on enzyme activity, gene expression and secretion of MMP2 from various tumor cells, resulting in reduced cancer cell invasion and metastasis." (PMID 36677584, 2023). "Moreover, MMP2 expression in CAFs and MMP9 expression in the tumour nest at the TSI was significantly associated with ENE + but not with TME activity-related features (TB, DR, and TILs)." (PMID 36765296, 2023). "In conclusion, stimulation of the P2X7 receptor can activate the P13K/AKT signaling pathway, decrease GSK3β activity, activate Wnt/β-catenin, increase VEGF level, activate JNK and Rho, and increase MMP2 expression, all of which are involved in tumor cell migration and invasion." (PMID 38273855, 2023). "NF-κB also plays an important role in regulating tumour cell infiltration by controlling the expression of many adhesion molecules, such as fibronectin and vitronectin responsible for the invasion of matrix metalloproteinases such as MMP-2 and MMP-9." (PMID 36675073, 2023). "Therefore, COX-2 inhibition reduces MMP-2 production, which, in turn, inhibits tumor invasion and metastasis." (PMID 37180721, 2023). "Grange and colleagues performed molecular characterization of microvesicles and identified specific mRNAs associated with tumor progression and metastasis, including VEGF, fibroblast growth factor-2 (FGF2), angiopoietin-1 (ANGPT1), ephrin-A3 (EFNA3), metalloproteinase (MMP)-2, and MMP9." (PMID 37762660, 2023). "Interestingly, the antibody was coupled through a matrix metalloprotease 2 (MMP2) enzyme-sensitive peptide, promoting antibody-triggered release in the tumor environment (rich in MM2)." (PMID 37896241, 2023). "At hypoxic tumor sites, HIF-1α activates MMP-2 and -9 to promote tumor metastasis." (PMID 37239383, 2023). "Moreover, HA stimulates EC tube formation via CD44 and CD168/TGFβ Receptor I signaling, which promote plasminogen activator-inhibitor-1 (PAI-1) expression and subsequently ICAM-1, VCAM-1, and MMP-2 expression, thereby promoting tumor angiogenesis." (PMID 37350937, 2023). "In this study, DABE also showed mild suppression of tumor growth and decreased plasma IL-6 and MMP-2 levels, suggesting that the PAR1 and PAR4 pathways may also be involved in Colon26 cell proliferation and inflammation induced by Colon26 cells to some extent." (PMID 36751299, 2023). "First, the nanovesicles engineered for PPa and LY co-delivery can specifically accumulate and retain at the tumor site via passive tumor targeting effect and MMP-2-mediated cleavage of PEG corona, thus maximizing their therapeutic benefits while minimizing the side effects." (PMID 37328484, 2023). "In addition, MMP-2 expression is related to tumor aggressiveness and grade and is reduced by CTX binding." (PMID 37444498, 2023).
tumor (continued). "Moreover, activated platelets can facilitate tumor cell extravasation after the extracellular matrix degradation by matrix metalloproteinase-2 (MMP-2)." (PMID 36975471, 2023). "As well as promoting invasion, an increase in MMP-2 secretion may also assist tumour survival by reducing apoptosis, proliferation and angiogenesis." (PMID 36302993, 2023). "We next examined the significance of TGF-β in the pro-tumorigenic effects of macrophages by evaluating the expression of CD163 and interleukin-10 (IL-10) (M2 macrophage markers), as well as matrix metalloprotease 2 (MMP2), which are known to promote tumor progression." (PMID 36980788, 2023). "MMP-2 is elevated in both CAFs and bladder cancer cell lines, which contributes to tumor growth." (PMID 36980785, 2023). "Tumor cells can produce MMP-2 or stimulate its production in surrounding cells." (PMID 37513440, 2023). "Matrix metalloproteinase-2 (MMP-2) overexpressed in cancer cells will cleave the peptide EGPLGVRGK off to activate the nanoprobe at the tumour site, resulting in PPa restoring its fluorescence and producing toxic singlet oxygen 1O2 upon 660 nm light irradiation." (PMID 36656411, 2023). "Additionally, aggressive UC is attributed to the tumor metastasis regulated by CEBPD-induced matrix metalloproteinase-2 (MMP2) overexpression." (PMID 36776299, 2023). "The CCL5-CCR5 pathway has been demonstrated to promote tumor invasiveness by activating intracellular calcium cascade (increased calcium levels) and CaMKII (Calcium/Calmodulin Dependent Protein Kinase Kinase II)-dependent matrix metalloproteinase 2 (MMP2) upregulation in tumor cells." (PMID 37700840, 2023). "Finally, the expression levels of the matrix-degrading enzyme metalloproteinase-2 (MMP-2), one of the promoters of tumor cell invasion, were also found to be more reduced after combined treatment with the two drugs compared with the single agents." (PMID 36672233, 2023). "Besides, overexpression of matrix metalloproteinase (MMP) plays an important role in the context of tumour invasion and metastasis, and MMP2 has been characterized as the most validated target for cancer." (PMID 37667197, 2023). "MMP exocytosis, especially MMP-2/9 exocytosis, is essential for tumor cell invasion and metastasis." (PMID 37691034, 2023). "Notably, CAR-T targeting CLTX requires the expression of MMP2 on tumor cells to bind and kill tumor cells effectively." (PMID 37190280, 2023). "Therefore, using gelatin as MMP2-sensitive linker has great potential to construct PEGylated and tumor-targeted drug nanocarriers for in vivo applications." (PMID 36839771, 2023). "Tumor-associated macrophages (TAMs) were identified by CD68, CD14, CD163 and HLA-DRA and cancer-associated fibroblasts (CAFs) were characterized by COL1A1, COL3A1, MMP2, and SPARC." (PMID 37007745, 2023). "Although given current data, it is impossible to affirm exactly the relationship between circulating miR-124 in EVPs and MMP-2 in the tumor microenvironment, it can be inferred that these molecules are involved in the effects of exercise on the tumor invasion process." (PMID 36936170, 2023). "Indeed, we observed significant downregulation of TGF-β1 and MMP2 in the tumor tissues treated with pevonedistat." (PMID 37686215, 2023). "In addition, therapy with altered PLGA-MOR-CTX nanoparticles led to increased caspase activation, cytoskeletal disruption, inhibition of MMP-2 action, and ROS production in the tumor tissue." (PMID 37228582, 2023). "Moreover, this indoleamine has shown an effect on collagen content and MMP2 positivity in tumors, suggesting a broader effect on tumor microenvironment." (PMID 37894275, 2023). "PTTG1’s contribution to tumor progression is attributed to both its promotion of genetic instability, due to altered sister chromatid segregation during mitosis, and its transcriptional activity on different targets, such as matrix metalloproteinase 2 (MMP-2)." (PMID 38069214, 2023).
tumor (continued). "M2 macrophages also release pro-angiogenesis factors such as IL23, PDGF and MMP2 that could further promote tumor progression." (PMID 37035187, 2023). "We established a xenograft tumour model by injecting TAMs, MMP2 inhibitor, and PBS for 2 weeks." (PMID 35999359, 2023). "Therefore, the overexpression of RECK had the capacity to modulate the expression of these proteins, including E-cadherin, N-cadherin, Vimentin and MMP2, thereby exerting inhibitory effects on the migration and invasion of tumor cells." (PMID 37904179, 2023). "Mmp12 and Mmp2 are involved in the generation of the tumor microenvironment." (PMID 36768216, 2023). "In addition to being a tumor marker in NPC, MMP-2 is also linked to lymph node metastases and a poor prognosis." (PMID 37228582, 2023). "MMP2 and MMP9 overexpression is associated with higher tumor grades." (PMID 37239013, 2023). "After stable knockdown of PSMA3-AS1, reductions in MMP-2/-9 levels were detected in tumor tissues." (PMID 37403106, 2023). "In addition, TAMs suppress the antitumor response by producing IL-10 and prostaglandin E2 and promote tumor cell invasion and metastasis by producing MMP-2 and MMP-9." (PMID 37046639, 2023). "In addition, the peptide linker can be cleaved by the overexpressed MMP‐2 in tumor tissue, resulting in the release of anti‐PD‐L1 antibody." (PMID 36437106, 2023). "Among these, MMP-2 and MMP-9 are highly associated with tumor dissemination and invasiveness." (PMID 37047801, 2023). "The binding of TGF-β and SDF-1 to the membrane receptors on the tumor triggers the expression of endothelial markers like VE-cadherin, matrix metalloproteinase (MMP2) and laminin subunit gamma-2 (LAMC2) that could degrade the ECM to form VM." (PMID 37035187, 2023). "Finally, when the CRISPR-Cas13a system was delivered by the CHAIN in vivo, it knocked down the targeted oncogene miR-21, restored PDCD4 and RECK, crippled downstream MMP-2, and eventually suppressed tumor growth." (PMID 37284454, 2023). "MMP2 is a key mediator of invasion, metastasis, tumor angiogenesis and VM in tumor cells." (PMID 37217473, 2023). "Furthermore, when we analyzed the transcriptomic data from TNBC subtype BRCA biopsies deposited in TCGA, we found that tumor expression of Foxp3 positively correlated with the expression of MMP-2 and MMP-9." (PMID 37766222, 2023). "Study showed that in the co-culture system of LUAD A549 cells, esophageal cancer cells, and mesenchymal stem cells (MSCs)-conditioned medium, MSCs induced cell apoptosis and downregulated MMP-2 in vitro, interestingly, this study also showed that MSCs enhanced tumor formation and growth in vivo." (PMID 37766868, 2023). "Moreover, both chalcones inhibit tumor cell invasion and migration, accompanied by downregulation of MMP-2 and MMP-9." (PMID 37373500, 2023). "Interestingly, after the peptide was cut by the MMP‐2 in tumour microenvironment, the aggregation state of QC probes was changed, resulting in an MMP‐2‐concentration‐dependent fluorescent emission." (PMID 38264683, 2023). "Therefore, the invasive ability of tumor cells should be proportional to the expression of MMP-2 and MMP-9." (PMID 36785788, 2023). "Moreover, MMP-2 can affect signaling pathways in cancer cells by promoting tumor cell growth, enhancing resistance to apoptosis, and improving angiogenesis." (PMID 37513440, 2023). "In recent studies, MMP‐2 has been used as a tumoral stimulus for tumor‐targeted drug release." (PMID 35600646, 2022). "It has been reported that in highly invasive tumors, the expression of MMP2 is increased in tumor cells with high expression of SLUG, suggesting that the relationship between SLUG and MMPs might play a potential role in tumor invasion and the EMT process." (PMID 36003306, 2022). "Importantly, it has been revealed that MMP-2 expression is positively controlled by Smad2 whilst MMP-9 is modulated via NF-κB p65/p50 transcription signaling in tumor tissues and cells of CRC." (PMID 35308223, 2022).
tumor (continued). "Notably, recent studies have shown that inhibition of MMP2/9 can reduce tumor burden and improve survival, promoting anti-tumoral immunity." (PMID 35572966, 2022). "These MMP results contrast with another study where tumor cells of CLM expressed MMP-2 and -9." (PMID 35884455, 2022). "Furthermore, our IHC results proved that high expression level of Mena was significantly correlated with EMT markers E-cadherin and Vimentin, and tumor invasive marker MMP-2, but uncorrelated with Ki67." (PMID 36620546, 2022). "MMP2 and MMP9 are gelatinases of matrix metalloproteinase family, which were initially associated with the invasive and metastatic properties of tumour cells, owing to their ability to degrade major protein components of the extracellular matrix and basement membranes." (PMID 36153370, 2022). "Additionally, miR-142 seemingly acts as a tumor suppressor by reducing the expression of MMP-2 and -9, thereby inhibiting tumor cell invasion." (PMID 36180575, 2022). "In contrast, MMP2 staining was mainly located in tumor cells and the extracellular matrix." (PMID 34980260, 2022). "Similarly, matrix metalloproteinase 2 (MMP-2) has been shown to play a vital role in tumor progression by regulating the tumor microenvironment, primarily by maintaining the connection between the tumor and stroma." (PMID 36551233, 2022). "Lastly, MMP9 can be also pro-tumour along with MMP2, and both of them are involved in metastasis." (PMID 35406451, 2022). "Whereas ROS-dependent signaling events may trigger angiogenesis (i.e., cell migration and proliferation) and influence MMP2 that affect growth factor and tumor promoter stimulation as well." (PMID 36452505, 2022). "GBM tumours are frequently found to have upregulation of MMP-2 and MMP-9." (PMID 36497413, 2022). "The expression of matrix metalloproteinase 2 (MMP2) in tumour models and OSCC tissues could be detected using these UCNP composites." (PMID 35884301, 2022). "In addition, MMP‐2 is overexpressed in malignant tumor tissues compared with blood and benign tissues and is also used as a biomarker for cancer therapy and diagnosis." (PMID 35600646, 2022). "MMP9 and MMP2 accelerate tumor metastasis by invading lymphatic vessels and small vessels." (PMID 35069767, 2022). "GNPs-P-DOX-GA nanoparticles could be degraded by tumor extracellular metal matrix protease-2 (MMP2) and release small size P-DOX-GA to facilitate tumor tissue penetration." (PMID 35237155, 2022). "Interestingly, we observed in tumor samples higher levels of MMP-2 and MMP-9, along with lower levels of MMP-14, their main activator." (PMID 36518899, 2022). "To assess whether the combined effects of CXCL12 and CXCL11 on tumor cell invasion involve MMPs as an intermediate, we focused on the gelatinases MMP-2 and MMP-9, which represent known targets of CXCL12 and CXCL11." (PMID 36539774, 2022). "VM formation of tumor was dependent on extracellular matrix MMPs and laminin 5γ2, which could be cleaved into γ2 and γ2x by activated MMP2." (PMID 36463205, 2022). "There is a compelling body of evidence supporting that activation of the multiligand/RAGE axis is important in tumor associated-angiogenesis modulation, by triggering upregulation of VEGF and MMP2, as well as disruption of VE-cadherin-catenin complexes, thereby favoring capillary tube formation." (PMID 35727208, 2022). "The use of siRNA (short interfering RNA) encapsulated liposomes to inhibit PAR-1 in tumor cells was associated with a reduced expression of angiogenic and metastatic genes (such as VEGF, Interleukin (IL)-8, and matrix metalloproteinase-2 (MMP-2)) and blood vessel density." (PMID 35203374, 2022). "Both MMP-2 and MMP-9 are known to be associated with tumor metastasis and angiogenesis." (PMID 36483979, 2022).